VASP (vasodilator stimulated phosphoprotein)
Description:
Ena/VASP proteins are actin-associated proteins involved in a range of processes dependent on cytoskeleton remodeling and cell polarity such as axon guidance, lamellipodial and filopodial dynamics, platelet activation and cell migration. VASP promotes actin filament elongation. It protects the barbed end of growing actin filaments against capping and increases the rate of actin polymerization in the presence of capping protein. VASP stimulates actin filament elongation by promoting the transfer of profilin-bound actin monomers onto the barbed end of growing actin filaments. Plays a role in actin-based mobility of Listeria monocytogenes in host cells. Regulates actin dynamics in platelets and plays an important role in regulating platelet aggregation.
Tractability: Small molecule: a structure with a bound ligand is known. Antibody: its Gene Ontology location is reachable by antibodies, with high confidence; the Human Protein Atlas places it where antibodies can reach. PROTAC: ubiquitination databases record sites on it; its protein half-life has been measured.
Gene: Protein-coding gene on chromosome 19 (45,506,579 to 45,526,991, forward strand). Ensembl gene ENSG00000125753.
Subcellular location: Cytoplasm; Cytoplasm, cytoskeleton; Cell junction, focal adhesion; Cell junction, tight junction; Cell projection, lamellipodium membrane; Cell projection, filopodium membrane
Subcellular location (Human Protein Atlas): Cell Junctions; Focal adhesion sites; Plasma membrane
Pathways (Reactome):
Cell-Cell communication: Cell-extracellular matrix interactions
Developmental Biology: Signaling by ROBO receptors
Immune System: Generation of second messenger molecules
Gene Ontology:
Molecular function: cadherin binding; profilin binding; protein binding; actin binding; identical protein binding; SH3 domain binding
Biological process: positive regulation of actin filament polymerization; actin polymerization or depolymerization; axon guidance; neural tube closure; protein homotetramerization
Cellular component: cell junction; extracellular exosome; focal adhesion; plasma membrane; actin cytoskeleton; cytosol; bicellular tight junction; cytoplasm; cytoskeleton; filopodium; filopodium membrane; glutamatergic synapse; lamellipodium; lamellipodium membrane; postsynapse
Genetic constraint (gnomAD): Loss-of-function variants: 27 observed, 49.88 expected, observed/expected ratio (o/e) 0.54, 90% interval 0.4 to 0.75. The upper end of that interval is the gene's LOEUF score, 0.75, which puts it in group 3 of 6, group 1 being the genes least tolerant of losing a copy. Missense variants: 488 observed, 493.85 expected, observed/expected ratio (o/e) 0.99, 90% interval 0.92 to 1.07. Synonymous variants: 233 observed, 197.2 expected, observed/expected ratio (o/e) 1.18, 90% interval 1.06 to 1.32.
Homologues: Orthologues: chimpanzee VASP (99% identical), dog VASP (90% identical), pig VASP (89% identical), mouse Vasp (88% identical), guinea pig VASP (87% identical), rat Vasp (87% identical), macaque VASP (80% identical), zebrafish vaspb (63% identical), tropical clawed frog vasp (56% identical), zebrafish vaspa (53% identical), Drosophila melanogaster ena (39% identical), Caenorhabditis elegans unc-34 (17% identical). Paralogues in human: ENAH (51% identical), EVL (49% identical), SPRED3 (21% identical), SPRED1 (19% identical), SPRED2 (19% identical).
Diseases named in the same sentence as VASP in open-access papers:
VASP is named in the same sentence as 99 diseases in open-access papers, as found by Europe PMC text mining. Sharing a sentence is not in itself a finding about the gene and the disease. The quoted sentences say what the papers report.
breast cancer (32 papers, 2013 to 2025). A primary or metastatic malignant neoplasm involving the breast. "VASP is upregulated in breast cancer tissues and cells and is associated with proliferation and metastasis of breast cancer cells." (PMID 31754343, 2019). "Here, we used several available databases to determine if VASP expression in breast cancer can be linked to patient survival or tumor type." (PMID 26336132, 2015). "The expression levels of the Ena/VASP protein family members Mena and EVL-1 have been linked to patient outcome in breast cancer, whereas VASP has been described as expressed in relatively high levels in normal as well as cancer tissue." (PMID 26336132, 2015). "CTX inhibits the ERα/VASP signaling pathway in hormone receptor-positive breast cancer cells (MCF-7) and reduces MMP2 expression, limiting cell migration and invasion." (PMID 40364211, 2025). "SNHG6 promotes breast cancer cell proliferation, migration, and invasion by acting as a sponge for miR-26a-5p, which inhibits vasodilator-stimulated phosphoprotein (VASP)." (PMID 36139687, 2022). "VASP is a key target protein that regulates the migration of various tumor cells and upregulated in breast cancer tissues and cells." (PMID 36059653, 2022). "Vasodilator-stimulated phosphoprotein (VASP) is overexpressed in high-motility breast cancer cells, including basal-like TNBC and HER2-positive subtypes." (PMID 34948368, 2021). "The role of VASP in breast cancer cell proliferation and migration and its regulation mechanism need further exploration." (PMID 31754343, 2019). "The results showed that knockdown of VASP significantly affected normal aggregation of F-actin in breast cancer cells MCF-7 and MDA-MB-231." (PMID 31754343, 2019). "Compared to the control group, knockdown of VASP can significantly inhibit the viability and colony forming ability of breast cancer cells MCF-7 and MDA-MB-231." (PMID 31754343, 2019). "Although our previous series of studies have shown that VASP plays an important role in the development and progression of breast cancer, the role of VASP in breast cancer and its regulation mechanism remains to be further explored." (PMID 31754343, 2019). "The results of wound healing assay showed that knockdown of VASP significantly inhibited the migration of breast cancer cells MCF-7 and MDA-MB-231." (PMID 31754343, 2019). "The results of qPCR showed that compared to adjacent tissues, VASP mRNA expression were significantly higher in 7 cases breast cancer samples (7/10)." (PMID 31754343, 2019). "In MCF-7 and MDA-MB-231 cells, VASP overexpression significantly reversed the inhibitory effect of CREB1 knockdown on the migration of breast cancer cells." (PMID 31754343, 2019). "The results suggested that miR-638 was downregulated in breast cancer cells, and its expression trend was negatively correlated with VASP." (PMID 31754343, 2019). "Immunofluorescence staining was used to further detect the distribution of actin fiber F-actin in VASP knockdown breast cancer cell lines." (PMID 31754343, 2019). "Although the incidence of lung metastasis was not high (3/8), it suggested that the invasion and metastasis ability of breast cancer cells decreased after VASP knockdown." (PMID 31754343, 2019). "Our previous series of studies have shown that VASP, as a key oncogene, plays an important role in the development of various tumors such as breast cancer." (PMID 31754343, 2019). "The expression of VASP within each sub-type of breast cancer tissues was also analyzed by the Breast Cancer Gene-Expression Miner v4.2 database." (PMID 31754343, 2019). "We first analyzed the expression of VASP in normal breast tissues and different sub-types of breast cancer tissues using the BRCA (breast invasive carcinoma) data from TCGA." (PMID 31754343, 2019). "To further analyze the mechanism of VASP in breast cancer, we investigated the crosstalk between the Transcription and post-Transcription regulation." (PMID 31754343, 2019).
breast cancer (continued). "In the preliminary work of this group, we found that the protein expression level of VASP in breast cancer tissues was significantly higher than that in normal breast tissues." (PMID 31754343, 2019). "In summary, VASP is overexpressed in breast cancer cells and tissues, positively correlated with tumor malignancy, and significantly associated with poor prognosis in breast cancer patients." (PMID 31754343, 2019). "Suppression of VASP is associated with TNF-α and HIF-1α induced inhibition of breast cancer cell adhesion and proliferation.Downregulation of VASP expression inhibits breast cancer cell migration and invasion." (PMID 30271395, 2018). "Taken together, these data suggest that berberine inhibits actin polymerization by blocking VASP activity in breast cancer cells." (PMID 27322681, 2016). "We found that berberine binds to VASP and inhibits actin filament elongation, especially in basal-like breast cancer cells." (PMID 27322681, 2016). "Due to the lack of appropriate antibody tools other phosphorylations of VASP (i.e. Y39) currently cannot be assessed for their use as predictive markers for breast cancer progression." (PMID 26336132, 2015). "Next, we tested if VASP phosphorylation at S157, S239 or S322 is altered during progression of breast cancer." (PMID 26336132, 2015). "At this point it is unclear if in invasive breast cancer cells and tissue VASP phosphorylation at both sites is exclusively regulated PKD2, since both also can be targeted by AMPK, a metabolic gauge associated with tumorigenesis." (PMID 26336132, 2015). "To determine if the expression levels of VASP can be predictive for breast cancer patient survival we analyzed a set of 3455 patient samples for which gene expression data was available." (PMID 26336132, 2015). "We also show that the phosphorylation status of VASP at S322 can be predictive for breast cancer progression to an aggressive phenotype." (PMID 26336132, 2015). "Our data indicate that VASP expression levels cannot be used as predictive markers for type or outcome in breast cancer." (PMID 26336132, 2015). "Additionally, VASP overexpression has been linked to increased invasion ability in MDA‐MB‐231 cells, lymph node metastasis in breast cancer (BC) patients, and enhanced BC cell migration via interaction with integrin α3, a cell adhesion receptor." (PMID 39792809, 2025). "Moreover, inhibitors targeting the EVH1 domain of Ena/VASP proteins have been developed and exhibited biological activity to suppress the migration of breast cancer cells." (PMID 39511483, 2024). "The overexpression of vasodilator-stimulated phosphoprotein (VASP) and fibronectin (FN) is related to the poor prognosis of breast cancer, BBR not only binds to VASP to induce changes in its secondary structure but also decreases the expression of FN to inhibit cell proliferation and migration." (PMID 35153781, 2022). "Berberine could bind directly to VASP and alter the secondary structure of VASP, resulting in inhibiting actin polymerization in breast cancer cells." (PMID 34948368, 2021). "In breast cancer cells, the proliferation and migration were significantly decreased when VASP was silenced by shRNA, which proves that VASP plays a role in cancer cell migration, and it may be associated with RAC1." (PMID 33171868, 2020). "The results of the increasing expression of VASP mRNA levels indicated that transcriptional activation may participate in the regulation mechanism of VASP in breast cancer." (PMID 31754343, 2019). "This suggested that in breast cancer tissues, VASP may have abnormal activation at the transcriptional and post-transcriptional levels." (PMID 31754343, 2019). "Our study explained the mechanism of CREB1/Lin28/miR-638/VASP network promoting the development of breast cancer, which further elucidated the mechanism of VASP as a key oncogene, and also provided a theoretical basis for expanding new approaches to tumor biotherapy." (PMID 31754343, 2019).
breast cancer (continued). "In addition, we observed the effects of VASP knockdown on the growth and metastasis of breast cancer cells by nude mice tumor-bearing experiments." (PMID 31754343, 2019). "Our study elucidated the mechanisms of the CREB1/Lin28/miR-638/VASP interactive network in the development of breast cancer, further explained the mechanism of VASP as a key oncogene, and provided new ideas for targeted therapy research against breast cancer cells growth and metastasis." (PMID 31754343, 2019). "In summary, we found that CREB1 regulated VASP expression in two ways in breast cancer." (PMID 31754343, 2019). "In view of the higher expression of VASP in breast cancer cell lines and breast cancer tissues, the expression level of VASP was negatively correlated with the prognosis of breast cancer patients, suggesting that VASP was closely related to the development of breast cancer." (PMID 31754343, 2019). "The results showed that the expression level of VASP in breast cancer tissues was significantly higher than that in normal breast tissues, and the expression level of VASP in HER2-Enriched and Basal-like breast cancer was higher than that in luminal A/B breast cancer." (PMID 31754343, 2019). "Here we investigated whether the anti-tumorigenic effects of berberine are mediated by binding VASP in basal-like breast cancer." (PMID 27322681, 2016). "First, we performed immunohistochemical analysis of VASP in 41 breast cancer samples." (PMID 27322681, 2016). "We previously showed that VASP is overexpressed in high-motility breast cancer cells." (PMID 27322681, 2016). "Therefore, our data suggests that high expression of VASP correlates with basal-like breast cancer (luminal A or B vs. basal-like, P < 0.05)." (PMID 27322681, 2016). "Given VASP's role in breast cancer cell motility and berberine's inhibition of cell motility, we tested whether VASP is regulated by berberine." (PMID 27322681, 2016). "Furthermore, we previously showed that VASP promotes breast cancer cell migration and that VASP levels are higher in basal-like than in luminal breast cancer." (PMID 27322681, 2016). "Furthermore, knocking down VASP expression in breast cancer cells inhibits cell migration and invasion." (PMID 27322681, 2016). "Thus, extension of lamellipodia toward EGF during chemosensing by breast carcinoma cells requires the Lpd-dependent recruitment of Ena/VASP proteins, despite the dispensability of Ena/VASP for Lpd-driven random 2D cell migration." (PMID 26996666, 2016). "Here we show that VASP is generally highly expressed in normal breast tissue and breast cancer." (PMID 26336132, 2015). "This is intriguing since Mena but not other Ena/VASP proteins have been implicated in EGF-dependent breast cancer invasion and metastasis." (PMID 24076656, 2013). "SNHG6 may contribute to breast cancer aggressiveness via the miR-26a/VASP axis." (PMID 38948025, 2024). "Therefore, exploring the molecular mechanism of VASP upregulation in breast cancer cells may be a new strategy for targeted therapy of breast cancer." (PMID 31754343, 2019). "Thus, inhibition of cytoskeletal rearrangements by targeting VASP-induced actin assembly could have therapeutic benefits in basal-like breast cancer." (PMID 27322681, 2016). "Therefore, we hypothesized that berberine acts as a tumor suppressor by binding VASP to impair cell migration in breast cancer cells." (PMID 27322681, 2016). "Mena but not other Ena/VASP proteins have been implicated in EGF-dependent breast cancer invasion and metastasis, however, how Mena is linked to the EGFR is unknown." (PMID 24076656, 2013). "Recently, nanomolar small-molecule inhibitors of Ena/VASP EVH1 domains have been developed to target invasion and extravasation of breast cancer cells." (PMID 37443774, 2023). "In breast cancer cells, RAPH1 has the capacity to promote three-dimensional (3D) cancer cell invasion through interaction with actin-elongating Ena/VASP proteins and the Scar/WAVE complex." (PMID 38062011, 2023).
breast cancer (continued). "VASP silencing inhibits the invasion of breast cancer MDA-MB-231 cells, and miR-638 can inhibit the expression of VASP." (PMID 36059653, 2022). "It has been demonstrated that vasodilator-stimulated phosphoprotein (VASP), MMP2, and MMP9 expression in breast cancer is diminished upon repression of STAT3 phosphorylation." (PMID 34488773, 2021). "The mRNA and protein levels of VASP was detected in normal breast cell MCF-10A, luminal A breast cancer cell MCF-7 and triple negative breast cancer cell MDA-MB-231." (PMID 31754343, 2019). "The results were similar with TCGA database, the VASP expression in Basal-like and HER2-Enriched breast cancer with higher malignancy was slightly higher than in luminal A and luminal B breast cancer." (PMID 31754343, 2019). "In basal-like breast cancer, BBR bound to vasodilator-stimulated phosphoprotein to induce the change of its secondary structure, and inhibited breast cancer cell proliferation and migration finally." (PMID 31319879, 2019). "The expression levels in breast cancer cells MCF-7 and MDA-MB-231 were higher than those in normal breast cells MCF-10A, and its expression trend was the same as VASP, and contrary to miR-638." (PMID 31754343, 2019). "Lnc015192 regulates miR-34a and subsequently targets Adam12 in breast cancer through a ceRNA mechanism, and studies have also shown that LncRNA BLACAT1 promotes glioma development by binding to miR-605-3p to regulate VASP expression and promote glioma development and progression." (PMID 36943627, 2023). "In addition, whereas ENAH and VASP promote the invasive potential of migratory breast cancer cells, EVL suppresses breast cancer invasion." (PMID 34854809, 2021). "Paralog-specific Ena/VASP inhibitors could have higher therapeutic potential, given the antagonistic roles of ENAH and EVL in promoting and suppressing breast cancer metastasis." (PMID 34854809, 2021). "In addition, we also found that vasodilator stimulated phosphoprotein (VASP) is a target gene of ERα signaling pathway, and CTX can inhibit breast cancer cell proliferation, migration, and invasion through ERα/VASP signaling pathway." (PMID 30806044, 2019). "Using MicroCosm Target Version to predict miRNAs that may target VASP, we found that miR-638 which was downregulated in breast cancer tissues, which may bind to the 3' UTR region of VASP and play a role in inhibiting VASP expression." (PMID 31754343, 2019). "In the present study, we found that CTX can significantly inhibit the proliferation, migration, and invasion of breast cancer cells, and its mechanism may be related to the ability of CTX to target ERα/VASP signaling pathway." (PMID 30806044, 2019). "Furthermore, we analyzed VASP expression in a variety of breast cancer cell lines using the CCLE database, the results showed that the VASP expression in triple negative breast cancer cell lines was significantly higher than in luminal cancer cell lines." (PMID 31754343, 2019). "Notably, our findings, in glia, implicate Drosophila Profilin and SRF signalling in MRL-mediated tumour dissemination, whereas interactions between Lpd and Ena/VASP and Scar/WAVE have been reported to be critical in the invasion of breast cancer cells." (PMID 28346426, 2017). "Lpd function in metastasis may be mediated via both Ena/VASP and the Scar/WAVE complex since we observed that Lpd mediates breast cancer invasion via both actin effectors." (PMID 26996666, 2016). "We found that under normal growth conditions in all breast cancer cell lines, VASP was only marginally or not phosphorylated at S157." (PMID 26336132, 2015). "Overall, these data suggest that VASP expression levels are not indicative for the subtype of breast cancer and are not suitable predictive markers for patient survival." (PMID 26336132, 2015). "Moreover, Ke Su's study identified that a decrease of VASP mRNA and protein expression mediated the TNF-α-induced adhesion and proliferation inhibition of breast cancer MCF-7 cells." (PMID 25051011, 2014).